LIG4 (DNA ligase 4)
Diseases named in the same sentence as LIG4 in open-access papers (continued):
Sharing a sentence is not in itself a finding about the gene and the disease.
Autoimmunity (3 papers, 2021 to 2025). The occurrence of an immune reaction against the organism's own cells or tissues. "Interestingly, LIG4 missense mutations leading to haploinsufficiency have recently been described to underlie autoimmunity in heterozygous LIG4 deficiency." (PMID 40093007, 2025).
B cell lymphoma (3 papers, 2016 to 2025).
brain tumors (3 papers, 2018 to 2026). "Compared to normal astrocytes, brain tumour lines had lower levels of the LIG4 coding gene, and these findings correlated with transcriptomic and genomic analyses." (PMID 36142793, 2022).
bladder cancer (2 papers, 2017 to 2024). "In addition to ATM, germline mutations in MRE11 has been shown to be predictive of radiotherapy response in bladder cancer, while inherited defects in DSB repair genes NBS1 and Lig4 have been linked to fatal complications from low doses of radiotherapy." (PMID 28055970, 2017).
dyskeratosis congenita (2 papers, 2007 to 2014). Dyskeratosis congenita (DC) is a rare ectodermal dysplasia that often presents with the classic triad of nail dysplasia, skin pigmentary changes, and oral leukoplakia associated with a high risk of bone marrow failure (BMF) and cancer. "Our work suggests that, in addition to dyskeratosis congenita, LIG4 and 17q24.2 syndromes also feature shortened telomeres; to confirm this, telomere length testing should be considered in both disorders." (PMID 24892279, 2014).
endometrial cancer (2 papers, 2020 to 2024). Primary or metastatic malignant neoplasm involving the endometrium (mucous membrane that lines the endometrial cavity). "In conclusion, this study unveils a novel mechanism by which SMYD3 contributes to endometrial cancer, shedding light on its dynamic regulation of the LIG4/XRCC4/XLF complex in the NHEJ pathway." (PMID 38191478, 2024).
lymphopenia (2 papers, 2012 to 2018). Reduction in the number of lymphocytes. "We describe a series of five LIG4 deficiency patients with a wide spectrum of clinical manifestations, ranging from short stature and asymptomatic CD4+ lymphopenia, to liver failure with sudden massive bleeding." (PMID 30719430, 2018).
sclerosing cholangitis (2 papers, 2018 to 2025). A chronic, autoimmune inflammatory liver disorder characterized by narrowing and scarring of the lumen of the bile ducts. "It is noteworthy that case series in the literature report liver involvement with jaundice, hepatomegaly, and sclerosing cholangitis in patients with LIG4 deficiency." (PMID 40093007, 2025).
soft tissue sarcoma (2 papers, 2013 to 2021). A malignant neoplasm arising from muscle tissue, adipose tissue, blood vessels, fibrous tissue, or other supportive tissues excluding the bones. "In mice, loss of a single allele of LIG4 results in the formation of soft tissue sarcomas, as a result of increased genomic instability." (PMID 33986995, 2021).
triple-negative breast carcinoma (2 papers, 2019 to 2025). An invasive breast carcinoma which is negative for expression of estrogen receptor (ER), progesterone receptor (PR), and human epidermal growth factor receptor 2 (HER2). "We investigated whether Lig4 might be a putative therapeutic target in a disease where HR is often compromised, namely, triple negative breast cancer (TNBC)." (PMID 30838131, 2019).
acute lymphoblastic leukemia (1 paper, 2025). Leukemia with an acute onset, characterized by the presence of lymphoblasts in the bone marrow and the peripheral blood. "We also found elevated Lig4 expression in acute lymphoblastic leukemias and corresponding cell lines, which has implications for interpreting DNA damage research conducted in these systems." (PMID 39866872, 2025).
acute T cell leukemia (1 paper, 2016). "After this first leukemia patient, several other patients have been identified with LIG4 deficiency and lymphoproliferation or lymphoid malignancies: EBV associated B cell lymphoma in two patients and acute T cell leukemia in another patient." (PMID 27855655, 2016).
AIDS (1 paper, 2022). A syndrome resulting from the acquired deficiency of cellular immunity caused by the human immunodeficiency virus (HIV). "In stratified analysis, XRCC5 rs16855458 was significantly associated with CD4+ T cell counts in AIDS patients, whereas LIG4 rs1805388 was linked to the clinical phases of AIDS patients." (PMID 36312587, 2022). "Here, we propose that the reason for this association was the functional changes of LIG4 protein resulting from the genetic variant directly affecting the clinical stage of AIDS." (PMID 36312587, 2022). "In this study, we conducted a case-control study in the northern Han Chinese population to investigate associations of 22 SNPs in XRCC7, XRCC6, XRCC5, XRCC4, and LIG4 genes with the risk of HIV-1 infection and the progression of AIDS." (PMID 36312587, 2022). "The results of our study revealed that there was a significant difference in genotype frequencies of LIG4 rs1805388 between MSM cases in clinical phase I+II and those in clinical phase III+IV, and AA/AG genotypes could significantly promote the disease progression of AIDS." (PMID 36312587, 2022).
ascariasis (1 paper, 2020). An infection that is caused by the roundworm Ascaris lumbricoides, many cases of which remain asymptomatic. "The role of IgE on protective immunity to Ascaris has not been sufficiently explored; however, considering previous associations between LIG4/ABHD13 and the IgE responses to Ascaris, our results suggest that IgE may play a role in reducing egg burden during ascariasis." (PMID 32425942, 2020).
CHARGE syndrome (1 paper, 2024). CHARGE syndrome is a multiple congenital anomaly syndrome characterized by the variable combination of multiple anomalies, mainly Coloboma; Choanal atresia/stenosis; Cranial nerve dysfunction; Characteristic ear anomalies (known as the major 4 C's). "However, OS has also been described in other genetic aetiologies that impair lymphocyte development, including IL7RA, IL2RG, ADA, DCLRE1C, RMRP and LIG4 deficiencies, and CHARGE syndrome." (PMID 38598033, 2024).
chronic myeloid leukemia (1 paper, 2021). "LIG4 deficiency contributes to abnormal DSB repair in chronic myeloid leukemia cells." (PMID 34373746, 2021).
colorectal adenocarcinoma (1 paper, 2016). The most common type of colorectal carcinoma. "However, human colorectal adenocarcinoma samples (N=173) displayed upregulation (60.1%) of LIG4 expression, compared with normal colorectal samples." (PMID 27009971, 2016).
cutaneous melanoma (1 paper, 2016). A primary melanoma arising from atypical melanocytes in the skin. "Although downregulation/mutation of LIG4 (and its partner XRCC4) was detected only in approximately 7% of cutaneous melanomas in TCGA database, inhibition/inactivating mutation of other members of D-NHEJ potentially impairing DSB repair activity by the pathway were detected, too." (PMID 27705909, 2016).
Cutis marmorata (1 paper, 2025). A reticular discoloration of the skin with cyanotic (reddish-blue appearing) areas surrounding pale central areas due to dilation of capillary blood vessels and stagnation of blood within the vessels. "In the literature, mucocutaneous manifestations of LIG4 deficiency are varied, including psoriasis, telangiectasias, rash, erythema, pallor, cutis marmorata, single palmar crease, hypopigmentation, and stomatitis." (PMID 40093007, 2025).
male infertility (1 paper, 2021). The inability of the male to effect fertilization of an ovum after a specified period of unprotected intercourse. "Additionally, LIG4 rs1805388 was also associated with susceptibility to male infertility." (PMID 35003222, 2021).
myelodysplastic syndrome (1 paper, 2022). A clonal hematopoietic disorder characterized by dysplasia and ineffective hematopoiesis in one or more of the hematopoietic cell lines. "Furthermore, this case suggests that LIG4 deficiency should be considered upon differential diagnosis of myelodysplastic syndrome in children." (PMID 36221079, 2022).
neoplastic syndrome (1 paper, 2018). A broad classification for disorders in which the development of neoplasms typically occur in association with a characteristic set of signs or symptoms. "Furthermore, analysis of genes associated with risk of other inherited neoplastic syndromes different to HBOC identified heterozygous pathogenic variants for MSR1 (4%, 2/52), LIG4 (4%, 2/52) and PDE11A (6%, 3/52) in the affected women in both groups." (PMID 30262796, 2018).
oral cancer (1 paper, 2023). "In oral cancer, a high level of LIG4 expression has been found to predict an unfavorable outcome." (PMID 37894339, 2023).
thyroid cancer (1 paper, 2024). "scRNA-seq analysis showed reduced expression of the LIG4 gene at the mRNA level in normal follicular thyroid cells and thyroid cancer cells, but its activity is tightly regulated at the protein level by XRCC4 and DNA-PKcs." (PMID 38380364, 2024).
urofacial syndrome (1 paper, 2020). "In an individual with biallelic variants in LRIG2, the causal gene for urofacial syndrome (MIM 615112), and a homozygous LIG4 missense variant, the affected child had recurrent episodes of urosepsis, secondary to severe vesicoureteral reflux, leading to left kidney hypoplasia and scarring." (PMID 32534991, 2020).
cancer (84 papers, 2003 to 2026). A tumor composed of atypical neoplastic, often pleomorphic cells that invade other tissues. "To obtain a comprehensive conclusion, we carried out a meta-analysis to systematically evaluate the relevance of LIG4 genetic variants with susceptibility of cancer." (PMID 25314918, 2014). "A growing number of studies have investigated the relevance of LIG4 T9I (rs1805388) and D501D (rs1805386) polymorphisms with cancer risk, however, the results are conflicting." (PMID 25314918, 2014). "After these discoveries, a mass of investigations were performed to estimate the association between LIG4 T9I and D501D polymorphisms and the susceptibility of various cancers." (PMID 25314918, 2014). "Heterogeneities were observed among several studies for LIG4 D501D polymorphism and overall cancer susceptibility (homozygous: P = 0.044; dominant: P = 0.048;) and T9I (homozygous: P < 0.001; recessive: P < 0.001; dominant: P < 0.001; allele: P < 0.001)." (PMID 25314918, 2014). "Our data suggests that LIG4 deficiency may promote a 'mutator phenotype' leading on to aggressive cancers." (PMID 34373746, 2021). "In accordance with our previous findings using gene-targeted cancer cell lines, we discovered a relative decrease in the fraction of genomic compared with intra-chromosomal fusions recovered from the DNA ligase 4-deficient cells with compromised classical NHEJ (CNHEJ) capacity." (PMID 33447828, 2021). "Polymorphisms in the LIG4 gene have been associated with increased risk for several cancers." (PMID 32605254, 2020). "However, in subgroup analysis, we found the LIG4 T9I was associated with a slightly decreased cancer risk among Caucasians." (PMID 25314918, 2014). "The presence of a LIG4 mutation, accounting for impaired DNA damage repair mechanisms and, therefore, a higher incidence of malignancies and sensitivity to ionizing radiation and chemotherapy, would have been relevant both for prevention and early diagnosis of cancer." (PMID 27855655, 2016). "Notable examples include the eukaryotic BRCA2 protein involved in various cancers, the DNA ligase 4, the archaeao-eukaryotic MCM replicative helicase, the bacterial DNA polymerase II, and the bacterial DNA repair RuvA protein." (PMID 41242521, 2025). "Wnt signaling has been linked to radioresistance in a variety of human cancers, and previous studies in human CRC cell lines have suggested that this effect is mediated through the regulation of Lig4, a ligase central to the DDR." (PMID 39047051, 2024). "Across cancers, we found that heterozygous loss events in XPC (2/5 tumor types), POLK (4/5), LIG4 (5/5), ATM (3/5), and TP53BP1 (3/5) were common in MYBL2 High tumors." (PMID 36358918, 2022). "Curcumin sensitized cancer cells to IR by altering the expression of DNA repair-related genes, including DNA ligase IV (LIG4), X-ray repair cross complementing 5 (XRCC5) and polynucleotide kinase/phosphatase (PNK)." (PMID 34572726, 2021). "Abnormal Wnt signalling results in increased expression of LIG4, conferring radioresistance in Wnt-driven cancers." (PMID 34373746, 2021). "It has been reported that LIGs (including LIG1, LIG3 and LIG4) play important roles in the occurrence and progression of many cancers." (PMID 34825062, 2021). "Decreased level of LIG4 at the protein level was then confirmed by Western blot in cancer cell lines in comparison to normal astrocytes." (PMID 30627327, 2018). "Surprisingly, a number of LIG4 and XRCC4 polymorphisms have also been identified that associate with a decreased risk of cancer." (PMID 28684677, 2017). "Down-regulation of XLF was associated with reduced LIG4 mRNA and protein expression levels, which is consistent with previous findings that XLF regulates LIG4 in cancer." (PMID 28526069, 2017). "Our results show that Wnt/β-catenin signalling enhances LIG4 expression, and upregulated LIG4 plays a key role in radioresistance in tissue stem cells and cancer cells." (PMID 27009971, 2016).
cancer (continued). "Additionally, experimental studies indicate that the knockdown of XRCC4 or epigenetic inhibition of LIG4/XRCC4/XLF complex formation increases cancer cell sensitivity to anticancer agents." (PMID 41513635, 2026). "Most recently, autosomal dominant LIG4 haploinsufficiency due to monoallelic LIG4 pathogenic variants were demonstrated in individuals with immune dysregulation but without cancer risk." (PMID 40925926, 2025). "Based on this similarity, we examined whether Lig4 is upregulated in cancers that phenotypically resemble these cell types." (PMID 39866872, 2025). "Targeting the PIPKIγ-LIG4 axis could significantly affect the efficacy of radiotherapy, especially in cancer types that heavily depend on robust DNA repair mechanisms." (PMID 40744919, 2025). "This is also the first report demonstrating the association of MRE11 rs2155209, XRCC5 rs828907, LIG4 rs1805388, ATM rs1801516 and RAD51 rs12593359 with survival in HNSCC, as well as the first to indicate that CHEK1 rs558351 may play a role in cancer disease." (PMID 37894339, 2023). "Lig4 inhibitor medication research holds great promise for cancer treatment." (PMID 37808268, 2023). "Typical examples are HBOC (BRCA121/222) and its related cancer susceptibilities designated as ‘HR-deficiency (HRD)’(RAD5034, RAD5135, RAD51C36,37/D38, BARD139, BRIP140, PALB241), Nijmegen breakage syndrome (NBS142) and LIG4 syndrome (LIG443)." (PMID 36042341, 2022). "Obviously, this bystander effectis harmful to normal tissues, but may be beneficial to induce cancer cell death inradiotherapy, especially for cancer cells that overexpress LIG4." (PMID 30038324, 2018). "Overall, in spite of these limitations, this analysis reached a precise conclusion that LIG4 D501D polymorphism has no obvious relevance with cancer risk and individual with LIG4 T9I genetic variant has a decrease cancer risk among Caucasians." (PMID 25314918, 2014). "In conclusion, despite several limitations, this meta-analysis suggested that LIG4 T9I genetic variant is associated with a decreased risk of cancer among Caucasians, however, the rs1805386 gene polymorphism is not a risk factor of cancer." (PMID 25314918, 2014). "Overall, our results suggested that there was no obvious relevance of LIG4 T9I polymorphism with cancer susceptibility." (PMID 25314918, 2014). "Although inhibitors of LIG4 are considered potential anticancer drugs, they are likely not effective in cancer cells with mutations, which may affect radiotherapy outcomes." (PMID 32355263, 2020). "There was no relevance of LIG4 T9I variants with overall cancer risk (homozygous: OR = 0.84, 95% CI = 0.55–1.27, P = 0.401; recessive: OR = 0.94, 95% CI = 0.81–1.09, P = 0.434; dominant: OR = 0.85, 95% CI = 0.58–1.25, P = 0.410; allele: OR = 0.93, 95% CI = 0.80–1.07, P = 0.306)." (PMID 25314918, 2014). "Similarly, LIG4 upregulation has been associated with tobacco-related cancers and not BaP specifically, though BaP is a component of tobacco smoke." (PMID 23403841, 2012). "The assembly of the DNA Ligase IV (LIG4)–XRCC4 complex is essential for NHEJ fidelity, however, the regulatory mechanisms governing this complex in cancer remain poorly understood." (PMID 41462961, 2025). "While the role of LIG4 in NHEJ repair and radiotherapy resistance is well-documented across various types of cancers, its specific influence on NHEJ in TNBC warrants further exploration." (PMID 40744919, 2025). "There are several studies showing the potential of combination therapy based on irradiation and various DDR inhibitors (DNA-dependent protein kinase (DNA-PK), ATM/ATR, LIG4, PARP1, CHK1) but mainly in other types of cancer." (PMID 32605254, 2020). "Although Lig4 inhibitors offer a lot of potential as cancer treatments, it is possible that they will not work against mutant cancer cells, which would compromise the effectiveness of radiotherapy." (PMID 37808268, 2023).
cancer (continued). "As such, understanding the biological ramifications for decreased Lig4 activity is critical for informing future therapeutics not only in cancer biology, but across multiple disease states." (PMID 30838131, 2019). "Only a limited number of studies have found a correlation between expression of LIG4, XRCC4, or XLF and cancer progression and patient outcomes, but a couple of studies have found that increased expression of these factors results in increased aggressiveness in tumors." (PMID 28684677, 2017). "Furthermore, CXorf56 protein overexpression suppressed the recruitment of phospho-DNA-PKcs, XRCC4, and LIG4, indicating that CXorf56-Ku70 binding impedes the recruitment of downstream responders of Ku70 to DNA damage sites, forcing cancer cells to choose HR rather than NHEJ for DSB repair." (PMID 37156759, 2023). "For example, TBPT significantly suppressed a series of genes involved in DNA double-strand break repair, including LIG4, CENPF, DNAJC2, RECQL, SMC6 and BRCA2 (≥ 2-fold), which are also considered vital targets for treating cancer cells without affecting normal cells." (PMID 26986511, 2016).